TEX264 (testis expressed 264, ER-phagy receptor)
Description:
Major reticulophagy (also called ER-phagy) receptor that acts independently of other candidate reticulophagy receptors to remodel subdomains of the endoplasmic reticulum into autophagosomes upon nutrient stress, which then fuse with lysosomes for endoplasmic reticulum turnover. The ATG8-containing isolation membrane (IM) cradles a tubular segment of TEX264-positive ER near a three-way junction, allowing the formation of a synapse of 2 juxtaposed membranes with trans interaction between the TEX264 and ATG8 proteins. Expansion of the IM would extend the capture of ER, possibly through a 'zipper-like' process involving continued trans TEX264-ATG8 interactions, until poorly understood mechanisms lead to the fission of relevant membranes and, ultimately, autophagosomal membrane closure. Also involved in the repair of covalent DNA-protein cross-links (DPCs) during DNA synthesis: acts by bridging VCP/p97 to covalent DNA-protein cross-links (DPCs) and initiating resolution of DPCs by SPRTN.
Synonyms: ZSIG11; FLJ13935
Tractability: Antibody: its Gene Ontology location is reachable by antibodies, with high confidence; UniProt predicts a signal peptide or a membrane-spanning region. PROTAC: ubiquitination databases record sites on it; its protein half-life has been measured.
Gene: Protein-coding gene on chromosome 3 (51,662,693 to 51,704,323, forward strand). Ensembl gene ENSG00000164081.
Subcellular location: Endoplasmic reticulum membrane; Cytoplasmic vesicle, autophagosome; Cytoplasm, cytosol; Nucleus; Chromosome
Subcellular location (Human Protein Atlas): Endoplasmic reticulum
Pathways (Reactome):
Hemostasis: Platelet degranulation
Gene Ontology:
Molecular function: protein binding; signaling receptor activity
Biological process: protein-DNA covalent cross-linking repair; reticulophagy
Cellular component: autophagosome membrane; chromosome; cytosol; endoplasmic reticulum; endoplasmic reticulum membrane; nucleus; replication fork; extracellular region; platelet alpha granule lumen; autophagosome
Genetic constraint (gnomAD): Loss-of-function variants: 13 observed, 25.91 expected, observed/expected ratio (o/e) 0.5, 90% interval 0.33 to 0.8. The upper end of that interval is the gene's LOEUF score, 0.8, which puts it in group 3 of 6, group 1 being the genes least tolerant of losing a copy. Missense variants: 340 observed, 419.62 expected, observed/expected ratio (o/e) 0.81, 90% interval 0.74 to 0.89. Synonymous variants: 159 observed, 175.08 expected, observed/expected ratio (o/e) 0.91, 90% interval 0.8 to 1.04.
Homologues: Orthologues: chimpanzee TEX264 (98% identical), dog TEX264 (88% identical), guinea pig TEX264 (85% identical), mouse Tex264 (83% identical), rat Tex264 (82% identical), rabbit TEX264 (67% identical), pig TEX264 (66% identical), tropical clawed frog TEX264 (49% identical), zebrafish tex264a (42% identical), Caenorhabditis elegans T24H7.9 (18% identical).
Diseases named in the same sentence as TEX264 in open-access papers:
TEX264 is named in the same sentence as 8 diseases in open-access papers, as found by Europe PMC text mining. Sharing a sentence is not in itself a finding about the gene and the disease. The quoted sentences say what the papers report.
lung carcinoma (2 papers, 2022 to 2025).
Alzheimer disease (1 paper, 2025). A progressive, neurodegenerative disease characterized by loss of function and death of nerve cells in several areas of the brain leading to loss of cognitive function such as memory and language. "RTN3 deficiency has been implicated in Alzheimer's disease (AD) 44, and decreased TEX264 expression has been observed in AD-associated neuroinflammation." (PMID 40959274, 2025).
autism (1 paper, 2022). Persistent deficits in social interaction and communication and interaction as well as a markedly restricted repertoire of activity and interest as well as repetitive patterns of behavior. "Furthermore, bioinformatics analyses of Tex264 gene expression profiles based on GEO datasets suggest that Tex264 may be involved in development of oligodendrocyte progenitor cells (OPCs) and neurons as well as in disorders associated with autism." (PMID 35837377, 2022).
colorectal cancer (1 paper, 2025). A primary or metastatic malignant neoplasm that affects the colon or rectum. "Nucleophagy mediated by TEX264 contributes to the stability of DNA replication forks, ensures genetic stability, and facilitates cell survival, highlighting its potential clinical relevance for patients with colorectal cancer." (PMID 40896397, 2025).
glioblastoma (1 paper, 2023). The most malignant astrocytic tumor (WHO grade IV). "Loperamide treatment of glioblastoma (GBM) promotes the UPR, and downstream ATF4 mediates the activation of the ER-phagy receptors FAM134B and TEX264 to promote ER degradation." (PMID 37794028, 2023).
insomnia (1 paper, 2020). A sleep disorder characterized by difficulty in falling asleep and/or remaining asleep. "The insomnia-associated gene of HEBP2 has shared protein domains with the insomnia-associated gene of TEX264, and TEX264 show evidence of co-expression with DALRD3." (PMID 32830860, 2020). "In conclusion, the current comprehensive study provides multiple lines of evidence for supporting DALRD3, LDHA, HEBP2, TEX264, and FGFR3 as insomnia-associated genes whose abnormal expression level may convey risk to insomnia." (PMID 32830860, 2020).
tumor (1 paper, 2022). "Given the effect of the TEX264 and SNX27 interaction on tumor cell migration, development of drugs that block this interaction could inhibit tumor invasion and metastasis in vivo." (PMID 35837377, 2022).
TEX264 also shares sentences with these, for which no sentence is quoted: cancer (1 paper).